CD1D (CD1d molecule)
Diseases named in the same sentence as CD1D in open-access papers (continued):
Sharing a sentence is not in itself a finding about the gene and the disease.
tumor (continued). "The antitumor effect of α-GalCer stimulation is exerted not only through direct cytotoxicity by NKT cells but also by the activation of NK cells, which can eliminate CD1d negative tumor cells." (PMID 36769513, 2023). "Next, we evaluated whether B2M, CD1D, and CD1B differential expression are impacted at the tumor cells or DCs levels in the TME." (PMID 37077920, 2023). "Nevertheless, in certain cases higher expression of CD1d can result in increased tumour cell lysis, whereas lack of CD1d expression in tumours leads to their escape from recognition promoting tumour progression." (PMID 37153585, 2023). "Using previously validated immune gene signatures from bulk RNA datasets to estimate immune cell abundances, we found that B2M and CD1D but not CD1B were significantly enriched on both tumor and DCs cells from patients responding to ICT." (PMID 37077920, 2023). "Regarding immunosuppressive cells in tumor-bearing CD1d−/− mice, WTMCGEP did not influence the abundance of tumor-infiltrating CD4+ and Forkhead box protein 3+ regulatory T cells." (PMID 37152373, 2023). "To investigate whether A. muciniphila excert anti-tumor through NKT cell activation, we used CD1d-knockout mice (which completely lack NKT cells) and CXCR6-knockout mice (which have a selective NKT deficiency in the liver)." (PMID 36531991, 2022). "CD1D can be expressed by antigen presenting cells (APCs) and tumour cells, but not usually solid tumours including MM." (PMID 35445563, 2022). "The predominant anti-tumor feature of iNKT cells mainly resides in their capacity to release large amounts of Th1 cytokines, such as IFN-γ, in addition to their ability to kill CD1d-positive tumor cells." (PMID 35874749, 2022). "The tumor restraining effect was abolished by treatment with anti-CD1d, anti-CD8 or anti-CD4 antibody, whereas it was not affected when an isotype-matched IgG control was used." (PMID 34983554, 2022). "In general, the expression of CD1d on moDCs was not significantly modulated by tumor cells, while a significant difference was observed between the WM278 and DexDC groups." (PMID 36194602, 2022). "No reduction in liver surface tumor nodules and liver tumor size were found in CD1d-/- and CXCR6-/- mice after A. muciniphila gavage." (PMID 36531991, 2022). "In contrast, type I NKT cells failed to hinder tumor growth of CD1d-negative U87 cells in the intracranial injection model." (PMID 36052072, 2022). "In addition to killing the CD1d expressing tumor cells directly, activated NKT cells are able to promote the killing effects of NK cells and CTLs against tumor cells." (PMID 35250965, 2021). "Furthermore, co-stimulation with α-GalCer further enhanced the anti-tumor function of anti-CD19 CAR-NKT cells, demonstrating that co-stimulation through CD1d and the CAR TCR can provide increased therapeutic benefit." (PMID 34680322, 2021). "In CD1d wild-type xenograft models, after sub-cutaneous injection of AB12 cell lines—a murine malignant mesothelioma cell line derived from asbestos-induced tumour in Balb/c mice —tumour growth was decreased by the combination of α-GC following each cycle of cisplatin." (PMID 34206956, 2021). "In addition to tumor regression, CAR.GD2 NKT cells also eliminated immunosuppressive CD1d-positive M2 macrophages in vitro." (PMID 34072042, 2021). "In contrast, iNKT cells failed to repress tumor growth of CD1d-negative U87 cells in the intracranial injection model." (PMID 33128583, 2021). "NKT cells recognize glycolipid antigens presented on CD1d and can reduce MCL tumor burden in vivo." (PMID 32326225, 2020). "This dependence on SAP for cytotoxic response is not restricted to murine iNKT cells, as human iNKT cells transfected with SAP-specific but not control siRNAs fail to kill CD1d+ tumor cells." (PMID 31569599, 2019). "Our present study suggests the CD1d- and PJA2-related tumour microenvironment might be crucial for IMPC." (PMID 30651076, 2019).
tumor (continued). "Considering that type I NKT cells have been reported to be able to eliminate CD1d-expressing tumor cells via multiple pathways, it seems that CD1d on the cancer cells is mainly recognized by type I NKT cells, resulting in enhancement of tumor immunity." (PMID 29520281, 2018). "A big improvement of this approach is CD1d-mediated cross-presentation of endogenous glycolipids and or α-GalCer from tumor cells to NKT cells, leading to DC maturation and consequently effective long-term T cell resistance to the tumor." (PMID 29018445, 2017). "Moreover, prolonged antitumor effects could be obtained when combining the CD1d-antitumor fusion protein treatment with a therapeutic peptide/CpG cancer vaccine, which favored the capacity of iNKT cells to transactivate cross-presenting DCs for efficient priming of tumor-specific CD8 T cells." (PMID 29163493, 2017). "The interaction between CD1d-glycolipid complex and the invariant TCR of iNKT cells stimulates interferon gamma (IFN-γ) production and the secretion of a large number of other cytokines (e.g. IL-12, IL-4, IL-17) that promote tumor eradication." (PMID 28549432, 2017). "Nonetheless, the expression of CD1d in the 5T33MM model was still high at the end stage of MM and lacked the potency to activate type I NKT cells and cause tumor cell lysis after stimulation with α-GalCer." (PMID 26895468, 2016). "CD1d blockade did not have any effect by itself on tumor growth or survival, but it improved control of the irradiated tumor (p < 0.05) and survival (p < 0.05) of mice treated with RT and anti-CTLA-4." (PMID 25349699, 2014). "CD1d-restricted natural killer T (NKT) cells lie at the interface between the innate and adaptive immune systems and are important mediators of immune responses and tumor immunosurveillance." (PMID 25389427, 2014). "Both immunostimulatory CD8α + and CD8α- DC subsets were increased, whereas expression of activation markers CD40, CD70, CD86, and of MHC Class I molecules in either subsets of tumor infiltrating DCs were not altered by CD1d blockade." (PMID 25349699, 2014). "Activation and tumor targeting of iNKT cells via recombinant α-galactosylceramide (αGC)-loaded CD1d-anti-HER2 fusion protein (CD1d-antitumor) is combined or not with OVA peptide/CpG vaccine." (PMID 25426294, 2014). "We observed that the expression of genes involved in NK crosstalk with DCs and tumour cells (DNAM1, CRTAM, CD96), promoting NK cell activation (NCR3(NKp30)) or modulating NKT activity (CD1d) was strongly and positively correlated with that of the 5 previously identified markers of good prognosis." (PMID 23758773, 2013). "Tumor cells that express CD1d are killed by iNKT cells, but this is not the case for NB cells that lack CD1d." (PMID 23805414, 2013). "Here, we show that the killing capacity of human iNKT cells can be extended against CD1d-negative tumor cells by their coating with αGC/CD1d-antitumor scFv fusion proteins." (PMID 23242316, 2013). "The correlation observed among CD1d expression and the higher levels of sCTLA-4 in B-ALL patients suggest a possible role of this soluble molecule as a marker of progression to malignancy, or as a marker of severity of the neoplastic disease." (PMID 23049754, 2012). "CD1d is widely expressed in humans and animals in both hematopoietic and non-hematopoietic cells, including multiple tumor types." (PMID 21695190, 2011). "For a CD1d-restricted protective response of iNKT cells in the B16F10-Nex2 system, endogenous lipid components of tumor cells should be recognized and we hypothesized that they could be glycosphingolipids expressed on tumor cells, particularly iGb3." (PMID 19968878, 2009). "That the anti-tumor effect depended on cytotoxic NKT cells is inferred from the inability of iGb3-treated BMDCs from CD1d-KO mice to show any protective activity (not shown)." (PMID 19968878, 2009).
tumor (continued). "Unlike conventional T cells that recognize peptide antigens presented by polymorphic MHC molecules, iNKT cells respond to lipid antigens bound to the non-polymorphic CD1d molecule, giving them a unique advantage in targeting tumor cells that present alternative or non-peptide antigens." (PMID 40297580, 2025). "We speculated that the amount of carried over anti-iNKT-TCR antibody among different experimental settings created the discrepancy in the cytotoxic activity of iNKT cells toward CD1d-negative tumor cells." (PMID 38319156, 2024). "Thus, tumour-specific iNKT cells can attack CD1d+ tumour cells, such as leukemia and lymphoma, without HLA restriction." (PMID 39215816, 2024). "Therefore, iNKT cells require an anti-iNKT TCR mAb to recognize and kill CD1d-negative tumor cells via CD32 in a reverse ADCC-dependent manner." (PMID 38319156, 2024). "The ability of CD1d to present both self and foreign lipid antigens allows NKT cells to participate in immune surveillance and regulation, contributing to the body’s defense mechanisms against infections, tumor surveillance, and the modulation of autoimmune responses." (PMID 39518994, 2024). "Even tumor cells express CD1d molecule, they could not present lipid antigens as efficiently as DCs do." (PMID 38332012, 2024). "γδ T cells can directly kill tumor cells in a major histocompatibility complex (MHC)-independent manner while NK T cells can be activated in a CD1d-dependent or -independent manner and this could explain the direct response of CD4-CD8- T cells against 1B3-transfected tumor cells." (PMID 39007281, 2024). "It should be noted that B16-OVA is a CD1d-negative tumor model, hence the malignant cells could not directly have been killed by iNKT cells." (PMID 37908728, 2023). "Moreover, other immune cells (CD3+/CD4+ helper T cells, CD3+/CD1d+ NKT cells, CD3−/CD56+ NK cells, CD3+/TCRγδ+ T cells, and CD3−/CD11c+/HLA-DR+ dendritic cells) may effectively cooperate to kill tumor cells." (PMID 37100864, 2023). "Arming iNKT cells with CAR may provide a potent anti-tumor therapy that can remediate the tumor microenvironment (TME) through simultaneous depletion of TAMs and tumor cells using TCR/CD1d and CAR recognition, respectively, as well as generalized elimination of both via NK receptors." (PMID 37147740, 2023). "We show that CD1d is expressed by the majority of patient MM, (myelo)monocytic AML, and CLL cells and that the bsTCE triggers type 1 NKT and Vγ9Vδ2-T cell-mediated antitumor activity against these patient tumor cells and improves survival in in vivo AML, MM, and T-ALL mouse models." (PMID 36868236, 2023). "However, natural killer T (NKT) cells, which recognize lipid antigens presented by non-classical class Ib MHC CD1d antigen-presenting molecules, have emerged as significant immune modulators in tumor immunity." (PMID 34208864, 2021). "Importantly, stimulation with PolyI:C, a dsRNA analogue commonly used for bystander activation of NK cells, did not increase killing of RMA and only minimally enhanced RMA-S killing in B6 mice or CD1d−/− but induced elimination of both MHC-I+ and MHC-I− tumor cells in MHC-I−/− mice." (PMID 33467442, 2021). "Importantly, vaccination of CD1d−/− mice does not induce anti-tumor responses, demonstrating that the presentation of α-GalCer to iNKT cells is essential." (PMID 34680322, 2021). "The CD1d- and PJA2-related tumour microenvironment might be crucial for IMPC." (PMID 30651076, 2019). "The differences in these two studies may include that within the intact mouse there is also a role for iNKT cells in killing CD1d-expressing TAMs independent of any direct anti-tumor interactions." (PMID 29559971, 2018). "Since the cytolysis and eradication of tumor cells via type I NKT cells was shown to be dependent on CD1d expression on their cell surface, it was suggested that CD1d expression might be a predictor of whether α-GalCer-activated type I NKT cells are able to eradicate tumor cells or not." (PMID 29535734, 2018).
tumor (continued). "To determine if blockade of CD1d in the context of radiotherapy and CD137 costimulation resulted in improved priming of anti-tumor CD8+ T cells in dLN of WT mice similar to that observed during anti-CTLA-4 blockade, we measured tumor antigen-specific production of IFNγ by dLN cells." (PMID 25349699, 2014). "Whereas MHC class I molecules present peptide Ags to T cells, the structurally similar CD1d molecules present a variety of lipids that include normal endogenous glycolipids, glycolipids from marine sponges and bacteria, or tumor-derived phospholipids, glycolipids and non-lipidic molecules." (PMID 24009709, 2013). "TM40D-MB tumor cells with downregulated CD1d expression were found to grow at a slower rate than TM40D (CD1d-hi) tumors, suggesting that downregulated CD1d expression may not affect tumor proliferation directly." (PMID 21695190, 2011). "Based on our findings of the tumor-promoting effects of anti-CD1d monoclonal antibody treatment of CD1d-expressing tumor cells, current therapeutic strategies based on globally inhibiting CD1d by antibody blockade are not recommended." (PMID 21695190, 2011). "Furthermore, we tested whether this phosphorylation blockade was mediated by expression of CD1d on tumor cells or soluble mediators and co-cultured iNKT cells with TRAMP-C2 in the presence of CD1d blocking antibodies or separated by transwell membranes." (PMID 20593019, 2010). "Gating on lineage marker-negative tumor cells revealed a clear signal of CD1d expression." (PMID 20593019, 2010). "However, previous studies also showed that some CD1d-restricted non-invariant NKT cells can suppress anti-tumor responses." (PMID 20593019, 2010). "This approach could also allow for a non-MHC-restricted recognition of diverse tumor targets through either the CAR NK-cell activating receptors or endogenous TCR receptors of NKT cells triggered by glycolipids presented via CD1d, improving the effector cells’ resistance to exhaustion." (PMID 40002679, 2025). "Additionally, a CD1d-specific engager not only enhanced Vγ9Vδ2 T cell-mediated killing of CLL and MM cells but also induced pro-inflammatory cytokine secretion and dendritic cell maturation, suggesting a dual role in both direct tumor cell lysis and immune system activation." (PMID 40227601, 2025). "In addition, in a different model disease, a correlation was observed among CD1d expression and higher levels of sCTLA-4 in B-ALL patients, suggesting a possible role of this soluble molecule as a marker of progression to malignancy, or as a marker of severity of this neoplastic disease." (PMID 25383768, 2014). "Alternatively, as TM40D tumor cells were able to metastasize to lung in a CD1d-dependent manner, it is possible that the direct cytotoxic functions of DN iNKT cells may be more important in targeting circulating tumor cells, rather than decreasing primary tumor burden." (PMID 21695190, 2011). "In contrast to this observation, others reported that iNKT cells cannot target CD1d-negative tumor cells, because iNKT cells express an invariant TCR that recognizes antigens presented on CD1d." (PMID 38319156, 2024). "As predicted, no tumor protection was induced by C24:2 in Traj18-KO mice (note that the absence of type I NKT cells in Traj18-KO mice did not affect CD1d expression)." (PMID 38127463, 2023). "Binding EC50 of all three bsTCEs to human monocytes was equal, whereas binding EC50 of the Vγ9 bsTCEs to human Vγ9Vδ2-T cells was ∼30- to 60-fold higher compared with CD1d-Vδ2 bsTCE; however, this did not affect degranulation EC50 and tumor lysis." (PMID 36868236, 2023). "This illustrates that type I NKT cells, like NK cells, are able to kill tumor cells via NKR activation, even in the absence of CD1d." (PMID 29535734, 2018). "Although, the mechanisms or tumor specific CD1d—glycolipid complex that helps NKT cells recognize and kill only CD1d-positive tumor cells and not normal cells is still enigmatic." (PMID 29018445, 2017).
tumor (continued). "We used surface staining against the B10/Breg markers CD5, CD1d and Granzyme B in combination with CD19 and were able to identify cells with a Breg phenotype in wild-type controls but not in tumor-bearing recipients of T and B cells (data not shown)." (PMID 27121060, 2016). "The CD1d-Vδ2 bsTCE triggered robust upregulation of the degranulation marker CD107a on both type 1 NKT and Vγ9Vδ2-T cells in co-culture with multiple CD1d+ (but not CD1d−) tumor cell lines with low-nanomolar and low-picomolar EC50s, respectively." (PMID 36868236, 2023). "They showed that engineered iNKT cells, irrespective of the CAR design, could kill tumor cells through GD2-directed CAR and CD1d-dependent TCRs." (PMID 37147740, 2023). "iNKT cells can directly kill CD1d-expressing cancer cells, but also restrict immunosuppressive myelomonocytic populations in the tumor microenvironment (TME) via CD1d-cognate recognition, promoting anti-tumor responses irrespective of the CD1d expression by cancer cells." (PMID 35615083, 2022). "There may well be more total “non-invariant” diverse CD1d-restricted NKT cells in the body than iNKT and their ability to make Th2 cytokines appears to impair tumor immunity, whereas such NKT making IFNγ stratifies with cancer patient survival, as does iNKT." (PMID 29559971, 2018). "Since the NKT cell ligand presented by the monomorphic CD1d can be used for all humans irrespective of HLA types, and also because NKT cell-targeted therapy does not directly target tumor cells, this therapy can potentially be applied to all cancer patients and any tumor types." (PMID 28993781, 2017). "NK cells increased in the tumor with or without the OVA/CpG-ODN vaccine, but most importantly OVA-specific CTL numbers increased two-fold in the tumors upon combined OVA/CpG-ODN vaccine and CD1d-anti-HER2 therapy as compared to vaccine alone." (PMID 25426294, 2014). "However, two studies directly comparing the efficacy of CAR-T cells and CAR-iNKT cells using tumor co-expressing CAR target and CD1d suggests this may not be the case." (PMID 39170618, 2024). "Importantly, in 7-day co-cultures of healthy donor-derived PBMCs (i.e., non-enriched, non-preactivated type 1 NKT and Vγ9Vδ2-T cells) and tumor cell lines, AML growth was controlled and MM growth further reduced in the presence of the CD1d-Vδ2 bsTCE even at low to very low E:T ratios." (PMID 36868236, 2023). "Although CD1d expression varies among tumor types, in B cell chronic lymphocytic leukemia (CLL), the most common hematologic malignancy, the expression of CD1d is lower than that in normal B cells or is absent, which might allow the tumor to escape from iNKT-mediated surveillance." (PMID 36830717, 2023). "While hematopoietic tumors express CD1d, many solid tumors are CD1d negative but can nonetheless be targeted by other mechanisms, including NKG2D engagement, or by indirect activation of iNKT cells by other CD1d‐expressing, antigen‐presenting cells present within the tumor microenvironment." (PMID 34535957, 2021).